LTC4S (leukotriene C4 synthase)
Description:
Catalyzes the conjugation of leukotriene A4 with reduced glutathione (GSH) to form leukotriene C4 with high specificity. Can also catalyze the transfer of a glutathionyl group from glutathione (GSH) to 13(S),14(S)-epoxy-docosahexaenoic acid to form maresin conjugate in tissue regeneration 1 (MCTR1), a bioactive lipid mediator that possess potent anti-inflammatory and proresolving actions.
Synonyms: MGC33147
Tractability: Small molecule: a structure with a bound ligand is known; a high-quality ligand is known; it has a high-quality binding pocket. Antibody: UniProt predicts a signal peptide or a membrane-spanning region. PROTAC: a small molecule that binds it is known.
Target class: Enzyme; Lyase
Safety:
Unwanted effects reported when the protein is acted on. In parentheses: how it was acted on, where the effect was seen, and who reports it.
urticaria (source: ClinPGx)
Gene: Protein-coding gene on chromosome 5 (179,793,980 to 179,796,647, forward strand). Ensembl gene ENSG00000213316.
Subcellular location: Nucleus outer membrane; Endoplasmic reticulum membrane; Nucleus membrane
Subcellular location (Human Protein Atlas): Nucleoplasm; Cytosol; Endoplasmic reticulum
Pathways (Reactome):
Metabolism: Biosynthesis of Lipoxins (LX); Biosynthesis of maresin conjugates in tissue regeneration (MCTR); Biosynthesis of protectin and resolvin conjugates in tissue regeneration (PCTR and RCTR); Synthesis of 5-eicosatetraenoic acids; Synthesis of Leukotrienes (LT) and Eoxins (EX)
Gene Ontology:
Molecular function: identical protein binding; leukotriene-C4 synthase activity; lipid binding; protein binding; glutathione peroxidase activity; glutathione transferase activity; enzyme activator activity
Biological process: leukotriene metabolic process; long-chain fatty acid biosynthetic process; leukotriene biosynthetic process; carboxylic acid biosynthetic process; cellular oxidant detoxification
Cellular component: endoplasmic reticulum; endoplasmic reticulum membrane; nuclear envelope; nuclear membrane; nuclear outer membrane; intracellular membrane-bounded organelle; membrane
Genetic constraint (gnomAD): Loss-of-function variants: 18 observed, 15.73 expected, observed/expected ratio (o/e) 1.14, 90% interval 0.79 to 1.68. The synonymous counts are far from expectation, so gnomAD's model fits this gene poorly and the ratio says little. Missense variants: 235 observed, 174.98 expected, observed/expected ratio (o/e) 1.34, 90% interval 1.21 to 1.5. Synonymous variants: 126 observed, 84.75 expected, observed/expected ratio (o/e) 1.49, 90% interval 1.29 to 1.72.
Homologues: Orthologues: chimpanzee LTC4S (99% identical), macaque LTC4S (98% identical), dog LTC4S (93% identical), mouse Ltc4s (88% identical), pig LTC4S (87% identical), guinea pig LTC4S (63% identical), zebrafish ltc4s (55% identical), tropical clawed frog ltc4s.2 (53% identical). Paralogues in human: MGST2 (43% identical), ALOX5AP (34% identical), MGST3 (25% identical).
Diseases named in the same sentence as LTC4S in open-access papers:
LTC4S is named in the same sentence as 38 diseases in open-access papers, as found by Europe PMC text mining. Sharing a sentence is not in itself a finding about the gene and the disease. The quoted sentences say what the papers report.
asthma (16 papers, 2006 to 2025). "Further, a 444A > C SNP polymorphism in the LTC4S gene (encodes for leukotriene C4 synthase enzyme) can potentiate asthma risk along with reduced sensitivity toward CysLT1R antagonist, Zafirlukast." (PMID 40568744, 2025). "Our objective was to determine the efficacy of a botanical seed oil combination against airflow obstruction in asthma, and to determine the pharmacogenomic effect of the leukotriene C4 synthase (LTC4S) polymorphism A-444C." (PMID 25485197, 2014). "A single nucleotide polymorphism (allelic variant C of leukotriene C4 synthase) has been identified that shows moderate association with aspirin-intolerant asthma." (PMID 17140424, 2006). "Moreover, epigenetic changes in the genes encoding CysLT1 and LTC4S confer susceptibility to asthma." (PMID 31336653, 2019). "A 444A > C SNP polymorphism in the LTC4S gene, encoding an enzyme required for the formation of a glutathione adduct at the C-6 position of the arachidonic acid backbone, is associated with severe asthma and altered response to the CYSLTR1 receptor antagonist zafirlukast." (PMID 27990118, 2016). "In light of widely varying LTM treatment responses and the important role of polymorphism in patients with asthma, we systematically reviewed the pharmacogenetic literature on LTM and performed a meta-analysis on LTC4S-444A/C gene polymorphism." (PMID 35887565, 2022). "We have previously investigated the role of polymorphic variation in the genes of the 5-lipoxygenase pathway e.g. ALOX5, LTC4S, CYSLTR1 in asthma and allergy susceptibility and as determinants of clinical responses to therapies targeting this pathway." (PMID 22206291, 2011). "For example, patients with aspirin-intolerant asthma show upregulation of leukotriene C4 synthase and excess leukotriene production, with responsiveness to leukotriene receptor antagonist therapy." (PMID 17140424, 2006). "Interestingly, a small subpopulation of mast cells comprised mostly of cells from asthma horses and displayed higher expression of e.g., the asthma associated genes FKBP5, RGS1 and LTC4S, suggesting a role in inflammation." (PMID 37758813, 2023). "There is evidence of an association of LTC4S, NOS2A, PTGDR, MET, COX-2, OSF-2, and LF polymorphisms and the risk of developing nasal polyps, especially when combined with chronic allergic rhinitis and asthma." (PMID 28400178, 2017). "Particulate matter with an aerodynamic diameter of <2.5 μm (PM2.5) exacerbates asthma symptoms, and a recent genome-wide study demonstrated that the effects of acute PM2.5 exposure are associated with changes in CysLT1 expression and methylation of CpG sites on the CysLT1 and LTC4S genes." (PMID 31336653, 2019). "Asthma is believed to have a strong genetic background, and hundreds of genes have been identified to be related with asthma, including GSTM1, IL10, CTLA-4, SPINK5, LTC4S, IL4R, and ADAM33." (PMID 24790987, 2014). "Leukotriene (LT) C4 synthase (LTC4S) catalyzes the conjugation of the fatty acid LTA4 with the tripeptide GSH to produce LTC4, the parent compound of the cysteinyl leukotrienes, important mediators of asthma." (PMID 24366866, 2014). "Leukotriene (LT) C4 synthase (LTC4S) is an integral membrane protein that catalyzes the conjugation reaction between the fatty acid LTA4 and GSH to form the pro-inflammatory LTC4, an important mediator of asthma." (PMID 24810165, 2014). "Our meta-analysis and systematic review found that LTC4S-444A/C may influence the treatment response of patients taking non-selective CysLT receptor antagonists for asthma, and patients taking LTMs not in combination with ICS for asthma." (PMID 35887565, 2022). "Our meta-analysis and systematic review suggest that LTC4S-444A/C may influence the treatment response of patients taking non-selective CysLT receptor antagonists for asthma and patients taking LTMs not combined with ICS for asthma." (PMID 35887565, 2022).
ischemic stroke (3 papers, 2012 to 2021). A stroke disorder caused by obstruction of blood flow to the brain, due to thrombotic (local blood clot formation) or embolic (due to a blood clot or other material traveling from another site) event. "A previous study also showed that the dysfunction or downregulation of LTC4S, one of the key enzymes of the 5-lipoxygenase pathway, was associated with increased risk of venous thromboembolism and ischemic stroke." (PMID 33732102, 2021). "Moreover, recent studies have identified several predisposing genes that are also corelated with an ischemic stroke risk, such as LTC4S, ALOX5, APOA1, APOB." (PMID 33808851, 2021). "In the non-hypertensive group, CCL11 rs3744508, LTC4S rs730012, FCER1B rs569108, TGFB1 rs1800469, LTA rs909253 and CCL11 rs4795895 were associated with ischemic stroke." (PMID 22769019, 2012).
breast carcinoma (2 papers, 2021 to 2022). "LTC4S is a component gene in an immune signature associated with clinical response in breast cancer." (PMID 35681785, 2022). "LTC4S expression is upregulated in PC compared to normal tissues, and is a component gene in a immune signature associated with clinical response in breast cancer." (PMID 33498739, 2021).
colon cancer (2 papers, 2013 to 2023). "LTD4 is a ligand for CysLT1R that up-regulates both LTC4S and CysLT2R in intestinal epithelial and colon cancer cells." (PMID 23829413, 2013). "We found that the expression of 5-LO, LTA4H, and LTC4S, central enzymes in LT formation, is potently up-regulated when HT-29 and HCT-116 colon cancer cells are grown as MCTS." (PMID 36849252, 2023). "We show for the first time that in human colon cancer cells, the differentiation agent ATRA acts in part by inducing both LTC4S, an enzyme responsible for the generation of CysLTs, and CysLT2R, a receptor for these ligands." (PMID 23829413, 2013). "In addition to CysLT2R, LTC4S could be induced by ATRA in colon cancer cells." (PMID 23829413, 2013).
nasal polyp (2 papers, 2012 to 2017). "Increased levels of leukotriene C4 synthase with elevated levels of LTC4, LTD4, and LTE4 with an overexpression of leukotriene producing enzymes such as 5-lipoxygenase (5-LO) and LTC4 synthase in nasal polyp tissue have been documented." (PMID 22829846, 2012).
Stroke (2 papers, 2020 to 2021). Sudden impairment of blood flow to a part of the brain due to occlusion or rupture of an artery to the brain. "Furthermore, the roles of other stroke-associated genes, such as SAMHD-1, DDAH-1, HMOX1, LTC4S, ACTB, KPNA2, and JUN, in mediating stroke secondary to SARS-CoV-2 infection are required to be further explored experimental using COVID-19 patient samples or SARS-CoV-2 animal models." (PMID 33732102, 2021).
Anxiety (1 paper, 2025). Intense feelings of nervousness, tension, or panic often arise in response to interpersonal stresses. "Importantly, pharmacological inhibition of leukotriene-C4 synthase ameliorates radiation-induced anxiety and memory impairments." (PMID 40390112, 2025). "Our results demonstrated that by direct supressing radiation-induced LTC4 synthesis with an LTC4S inhibitor, a significant improvement in working memory performance and alleviation of radiation-induced anxiety-like behaviors were observed in mice that received crainial irradiaiton." (PMID 40390112, 2025).
atherosclerosis (1 paper, 2025). A disease characterized by the build-up of fatty material and calcium deposition in the arterial wall resulting in partial or complete occlusion of the arterial lumen. "GWAS studies based on carotid intima-media thickness (CIMT), an early marker of atherosclerosis, identified SNP in LTC4S gene (leukotriene C4 synthase) associated with CIMT in women, but not in men." (PMID 41460411, 2025).
atherosclerotic heart disease (1 paper, 2012). "In conclusion, we have demonstrated that LTC4S and CysLT1 receptor gene expression is up-regulated in the heart and can be further enhanced by bouts of hypoxic stress in a mouse model of atherosclerotic heart disease." (PMID 22848603, 2012).
atopic dermatitis (1 paper, 2025). "Single-cell RNA sequencing (scRNA-seq) data from lesional atopic dermatitis (AD) skin biopsies, as reported in a previously published study, were re-analyzed to assess the expression of 5-lipoxygenase (5-LO/ALOX5) and leukotriene-C4-synthase (LTC4S)." (PMID 41296013, 2025). "However, scRNA-seq analysis of lesional atopic dermatitis skin biopsies did not detect mRNA expression of 5-LO/ALOX5 or LTC4S in keratinocytes." (PMID 41296013, 2025).
basophilic leukemia (1 paper, 2013). "ATRA has previously been shown to induce mRNA expression, protein expression, and promoter activity of LTC4S in rat basophilic leukemia cells." (PMID 23829413, 2013).
bronchitis (1 paper, 2017). An acute or chronic inflammatory process affecting the bronchi. "Significant differences in the prevalence and risk of bronchitis were found in genotypes of LT-α and TNF-α, but not in ALOX5, LTC4S, TBXA2R, ADAM33, NOS1 and ORMDL3 in the Inuit populations residing both in Greenland and in Denmark." (PMID 28740106, 2017).
colitis (1 paper, 2024). Inflammation of the colon. "Neut-c4, also prevalent in the early colitis phase, expressed genes associated with phagocytosis and reactive oxygen species (ROS) generation (Gngt2, Ltc4s, Gpr84)." (PMID 38674054, 2024).
glioma (1 paper, 2023). A benign or malignant brain and spinal cord tumor that arises from glial cells (astrocytes, oligodendrocytes, ependymal cells). "Therefore, the elevated expression of LTA4H/LTA4H and LTC4S/LTC4S can be considered as specific to GBM and glioma, respectively." (PMID 36765904, 2023).
prostate carcinoma (1 paper, 2023). A carcinoma that arises from epithelial cells of the prostate gland. "Previous studies confirmed that EPHX2, RXRA, LTC4S and SLC25A17 were abnormally expressed in prostate cancer tissues and affected the malignant biological behaviour of prostate cancer cells and prognosis of patients." (PMID 36643625, 2023).
tumor (7 papers, 2018 to 2025). "Research indicates that SELENOP+ Mac can promote anti-tumor immunity by highly expressing FOLR2, IL32, CD3D, and LTC4S and are therefore considered to have anti-tumor effects." (PMID 38755647, 2024). "The intersection set analysis of the bioinformatics database and transcriptome array data identified six common genes, FSTL1, GDF15, IQSEC2, KDM3A, LTC4S and TCTEX1D4, in which most of them were involved in tumor cell proliferation and growth." (PMID 38201443, 2023). "These genes were FSTL1, GDF15, IQSEC2, KDM3A, LTC4S and TCTEX1D4, in which most of them were involved in tumor cell proliferation and growth." (PMID 38201443, 2023). "While down-regulation of genes such as CYP4A11, PLA2G4A, PLA2G3, LTC4S, CYP27A1, HMGCS2 and PDPK1 reduced patient overall survival time in most tumor types." (PMID 31074374, 2019). "The expression of C3 allows their involvement in complement activation within the tumor microenvironment, thereby influencing tumor cell lysis and immune cell activation.ALOX5AP and LTC4S participate in arachidonic acid metabolism, modulating inflammatory responses and immune cell functions." (PMID 41394809, 2025). "In the light of this evidence, we observed different cellular localization of OAT, LTC4S and TPD52 in PCa cells procured from AA and CA, which may imply a possible role in tumor aggressiveness in AA but it needs further studies." (PMID 30397274, 2018).
respiratory disease (2 papers, 2016 to 2022). "Aspirin-exacerbated respiratory disease is explained in part by overexpression of 5-lipoxygenase and leukotriene C4 synthase (LTC4S), resulting in constitutive overproduction of cysteinyl leukotrienes (CysLTs) and driving the surge in CysLT production that occurs with aspirin ingestion." (PMID 27965779, 2016).
LTC4S also shares sentences with these, for which no sentence is quoted: airway hyperresponsiveness (2 papers); cancer (2); allergic asthma (1); Allergy (1); Alzheimer disease (1); angioedema (1); Cerebral ischemia (1); cholestasis (1); colorectal cancer (1); COVID-19 (1); dermatitis (1); infection (1); inflammation (1); injury (1); memory impairment (1); pancreatic tumour (1); Pruritus (1); rheumatoid arthritis (1); rhinitis (1); urticaria (1); venous thromboembolism (1).